MTOR (mechanistic target of rapamycin kinase)
Diseases named in the same sentence as MTOR in open-access papers (continued):
Sharing a sentence is not in itself a finding about the gene and the disease.
glioma (continued). "Aberrant expression of circRNAs played vital roles in proliferation, cell cycle, invasion and metastasis of glioma through modulating complementary miRNAs or target mRNAs that were firmly related to cancer-associated signaling pathways, such as PI3K/AK/mTOR, Wnt/β-catenin, Notch pathways." (PMID 32061256, 2020). "Moreover, we stated that the AKT/mTOR signalling pathway contributed to MOX-induced autophagy in glioma cells." (PMID 32913473, 2020). "Its effect on mTOR signaling in glioma cells was studied next." (PMID 33159013, 2020). "In our study, we demonstrated that miR-450a-5p regulated the autophagy occurrence in glioma by targeting EGFR-mediated PI3K/AKT/mTOR pathway, thereby regulating the proliferation, apoptosis, and migration of glioma cells and enhancing the sensitivity of glioma cells to gefitinib." (PMID 32820249, 2020). "Loss of PTEN and activated PI3K/AKT/mTOR are required for up-regulation of VEGFR2, and then activating NF-κB-dependent transcriptional activity to induce the loss of sensitivity of chemotherapy in glioma." (PMID 30819137, 2019). "Further to this, miR-128 mediated temozolomide-induced cell death in glioma cells via inhibition of mTOR signaling and suppression of insulin-like growth factor 1, phosphoinositide-3-kinase regulatory subunit 1, rapamycin-insensitive companion of mTOR and mTOR." (PMID 35582140, 2019). "Additionally, lncRNA CRNDE was shown to impart pro-oncogenic abilities in gliomas by modulating mTOR signaling." (PMID 30734202, 2019). "In contradiction with data obtained for p-70S6K1, levels of p-4E-BP1 correlate with glioma grade and with patient overall survival, making it a potential prognosis factor to select patients who might benefit from mTOR inhibitor therapies." (PMID 31795417, 2019). "We additionally investigated the effects of mTOR inhibition in glioma cell lines G55 and T98G." (PMID 31510109, 2019). "Our findings also reveal drug-actionable mutations, and advocate for therapeutic targeting of the MAPK/TSC/mTOR pathway for high-grade epithelioid gliomas that may otherwise behave aggressively when treated only with conventional therapy." (PMID 31258848, 2019). "Although glioma cells with under-expressed hsa_circ_0037251 or over-expressed miR-1229-3p exhibited the down-regulated abilities of progression, capabilities for proliferation, invasion and migration were significantly restored by transfection with mTOR OV." (PMID 31875034, 2019). "Furthermore, transfection with mTOR overexpression vectors can restore the abilities of glioma cell progression even if hsa_circ_00037251 was knocked down using siRNAs." (PMID 31875034, 2019). "In addition, the presented results also revealed that mTOR is the downstream target of the circRNA-miRNA network, and the tumour-promoting function on glioma can be rescued after transfection with mTOR OV." (PMID 31875034, 2019). "The compound promoted the glioma cell cycle arrest via regulating phosphoinositide 3-kinase/protein kinase B (Akt)/mammalian Target Of Rapamycin (mTOR) signaling pathway and induced anti-migration effect via mitogen-activated protein kinases (MAPK) signaling pathway." (PMID 30755827, 2019). "In this regulatory axis, the proliferation, invasion and migration capabilities of glioma cells were significantly altered by regulating the expressions of miR-1229-3p and mTOR while transfection with miR-1229-3p mimics or mTOR siRNAs significantly promoted glioma cell apoptosis and G1 phase arrest." (PMID 31875034, 2019). "An association between the PI3K/Akt/mTOR signaling and tumor malignancy is confirmed by studies documenting an upregulation of pAKT, pmTOR, and p-p70S6K in high-grade gliomas (grades III and IV) compared with low-grade gliomas (grades I and II)." (PMID 31387280, 2019). "And overexpression of miR-1229-3p or low-expressed mTOR inhibited the glioma cell progression." (PMID 31875034, 2019).
glioma (continued). "Since hypoxic and nutrient-deprived areas dominate the glioma microenvironment, pharmacological mTOR inhibition could ultimately generate pro-survival effects in tumor cells." (PMID 31510109, 2019). "The identified hsa_circ_0037251/miR-1229-3p/mTOR axis may provide a potential biomarker and therapeutic target for glioma." (PMID 31875034, 2019). "Indeed, pharmacological inhibition of EGFR and mTOR had antiproliferative effects in glioma cells in vitro, and in some studies synergized with chemotherapy or radiation." (PMID 31510109, 2019). "LncRNA CRNDE, highly expressed in few cells in MGH26 and MGH28, was previously found to promote glioma cell growth and invasion through mTOR signaling and might serve as a potential novel therapeutic target for glioma." (PMID 31888172, 2019). "Further validation is required, but our results indicate that 2HG could serve as a potential noninvasive MRS-detectable metabolic biomarker of IDHmut glioma response to PI3K/mTOR inhibition." (PMID 31324855, 2019). "In addition, SRT2183 exposure decreased the phosphorylation levels of mTOR in both glioma cells at 12 and 24 h postexposure." (PMID 31319814, 2019). "Based on the findings, we propose that STAT6 downregulation resulting from DNA methyltransferase (DNMT)-mediated hypermethylation of promoter CpG islands facilitates accumulation of HIF-1α through mTOR activation in hypoxia and consequent enhancement of glioma cell survival." (PMID 31530290, 2019). "In summary, the results indicated that hsa_circ_0037251 may exert its regulatory functions in glioma progression through sponging miR-1229-3p and finally modulated the expression of mTOR." (PMID 31875034, 2019). "Many studies showed that chlorpromazine could inhibit the Akt/mTOR pathway and induce autophagic cell death in glioma cells, and inhibit the TMZ-resistant glioma cells growth and proliferation in orthotopic mouse brain tumor models." (PMID 30233327, 2018). "Similarly, another study found MST1 binds to AKT and attenuated the AKT and mTOR activity in glioma cell." (PMID 29896440, 2018). "AMPK and mTOR are one of master players in metabolic reprogramming in glioma." (PMID 30286133, 2018). "Moreover, these authors demonstrated that 4EBP1 phosphorylation increased with the histological grade and that mTOR phosphorylation was higher in grade III/IV glioma compared with grade II." (PMID 30662577, 2018). "In addition, our current finding showed that mTOR and Bcl‐2 were regulated by miR‐497 directly, highlighting the potential role of miR‐497 overexpression for glioma to develop a TMZ‐resistance phenotype." (PMID 28064447, 2017). "Our pathway enrichment analysis of miR-455-3p targets also found several relevant biological signaling pathways including pathways in cancer, focal adhesion, pancreatic cancer, glioma, basal cell carcinoma, and Mapk-, Wnt- and mTOR-signaling, suggesting alteration of liver architecture." (PMID 28596526, 2017). "Besides the list of driver genes, Drgap also reported 215 driver pathways in glioma, such as Hedgehog signaling pathway, mTOR signaling pathway, glioma and acute myeloid leukemia." (PMID 29046615, 2017). "Rad, an inhibitor of mTOR, was recently found to significantly increase iNOS expression, and to reduce IL-10 expression, suggesting that Rad prevents the acquisition of an M2 phenotype in response to glioma factors promoting classic M1 activation." (PMID 28555105, 2017). "However, treatment with one of cannabinoids, ∆9-tetrahydrocannabinol (THC), is capable of inducing autophagy-dependent cell death via ER stress and inhibition of AKT/mTOR in glioma cells." (PMID 28629173, 2017).
glioma (continued). "In addition, since the PI3K-Akt-mTOR signaling pathway is known as a crucial negative regulator of autophagy, we detected the activation of Akt, mTOR and p70S6K in glioma cells." (PMID 28767320, 2017). "Because excessive activation of the PI3K/AKT/mTOR pathway is common in gliomas, the combined use of ERβ agonists may be a viable and effective treatment option to combat TMZ chemoresistance." (PMID 29113424, 2017). "Hence, we propose, that sCPE enhances RPS6 activation via mTOR signaling and reduces aerobic glycolysis thereby constituting a novel modulator of glioma cell migration." (PMID 28978054, 2017). "Next, we successfully acquired mTOR and Bcl‐2‐overexpressed glioma cells." (PMID 28064447, 2017). "To verify this, we performed mTOR and Bcl‐2 loss‐of function experiments in U87‐TR and SF295‐TR cells to investigate whether the silencing of mTOR and Bcl‐2 in glioma cells could regulate the chemotherapy resistance of glioma cells in vitro." (PMID 28064447, 2017). "The results indicated that mTOR-targeted therapy led to increased Gln metabolism and rendered glioma cells Gln-dependent, which could be an approach for effective therapy options." (PMID 27752843, 2017). "Additionally, sCPE diminishes glioma cell migration associated with a negative regulation of Rac1 signaling via RPS6, since both inhibition of mTOR and stimulation of Rac1 results in a reversed effect of sCPE on migration." (PMID 28978054, 2017). "Thus, mTOR inhibition prevented glioma growth by inhibiting M2 polarization of microglial cells, thereby increasing their anti-tumor cytotoxic potential." (PMID 28555105, 2017). "Interestingly, RTK-PI3K/Akt-mTOR pathways are well known to promote invasive phenotypes of the glioma cells." (PMID 29207533, 2017). "The elevated 2-HG and proliferation levels were significantly reduced (near to 75% and 80%, respectively) after 48-h mTOR inhibitor treatment which confirmed our findings about the 2-HG reducing effect of rapamycin treatment in other 2-HG producing tumour type, in glioma cells." (PMID 28578659, 2017). "Our results – concerning the potential roles of mTOR activity and 2-HG production in migration of malignant cells – confirm the recently published data about the enhanced migration capacity of mIDH1 transfected glioma cells." (PMID 28578659, 2017). "Our previous studies have shown that Tspan8 is over-expressed in multiple human malignant glioma tissues, as well as in human glioma cells, which forms a complex with Rictor (a mTOR component) and integrin α3 to mediate mTOR activation, cell growth, and TMZ resistance." (PMID 27532105, 2016). "A recent study revealed that GSK3β could inhibit glioma progression via regulation of mTOR/p70S6K1 signaling pathway." (PMID 27792996, 2016). "Finally, the protein production of TELO2 and mTOR in human normal brain and four glioma cell lines, LN229, U87MG, GBM8401, and U118MG through wet lab approach using Western blotting." (PMID 27329594, 2016). "Therefore, the PI3K/Akt/mTOR pathway is regarded as an important amenable pathway for pharmacological interventions in gliomas." (PMID 26830677, 2016). "RGS4-mediated glioma cell invasion is signaled by mTOR activation." (PMID 27105500, 2016). "In the present study, we showed GSK621 largely inhibited mTOR activation in glioma cells, which could partially explain its anti-glioma cell activity." (PMID 27532105, 2016). "Furthermore, we observed that the overexpression or knockdown of miR-128 expression affected TMZ-repressed mTOR signaling, suggesting that miR-128-targeted mTOR signaling is involved in TMZ-mediated glioma cell death." (PMID 27893811, 2016). "Indeed, we demonstrated that overexpression of miR-129 or knockdown of Notch-1 not only inhibited mTOR activity but also increased Beclin-1 protein levels in glioma cells." (PMID 26824182, 2016).
glioma (continued). "The effect of GOLPH3 on enhancing migration and invasion of glioma cells could be abolished by either treatment with the mTOR inhibitor INK128 or by YB-1 knockdown." (PMID 28983350, 2015). "Furthermore GOLPH3 promotes the migratory and invasive behavior of glioma cells in vitro and this effect is abolished by either treatment with the mTOR inhibitor INK128 or by YB1 knockdown." (PMID 25691054, 2015). "Although further investigations are required, this mechanism could represent another way for metformin to modulate the mTOR pathway in glioma cells." (PMID 25867026, 2015). "Because cediranib targets both PDGF and VEGF signaling, inhibition of which can have downstream inhibitory effects on the PI3K/Akt/mTOR pathway, we assessed whether cediranib treatment affected Akt kinase activation in 4C8 glioma cells." (PMID 25490024, 2014). "We have previously shown that CM harvested from glioma cells under basal conditions (C-CM), as well as CM from glioma cells activated with LPS/IFNγ (LI-CM), increased the phosphorylation of mTOR at ser 2448, an index of mTORC activation, in microglial cells in 2-h experiments." (PMID 25051975, 2014). "Aberrant PI3K/Akt/mTOR pathway has been shown to contribute to the resistant phenotype in glioma." (PMID 24418474, 2014). "Therefore, the EGFR/PI3K/Akt/mTOR pathway is regarded as the most amenable pathway to pharmacologic intervention in glioma." (PMID 24418474, 2014). "Since inhibition of mTOR is a way to avoid possible side effects associated with inhibition of PI3K-Akt, we tested whether rapamycin would cause radiosensitivity in glioma cells." (PMID 24418474, 2014). "Consistent with the findings in peripheral macrophages, here we show that the inhibition of mTOR polarizes glioma-activated microglial cells towards the M1 phenotype endowed with cytotoxic activities, thus preventing the induction of the M2 status that promotes tumor growth." (PMID 25051975, 2014). "An upstream regulator of mTOR is the tumor suppressor gene PTEN (phosphatase and tensin homologue deleted on chromosome 10), which is mutated or deleted in a great number of human tumors, including gliomas, the most aggressive type of primary brain tumors." (PMID 24349488, 2013). "Can inhibitors of the mTOR/PI3K axis be used to treat gliomas?" (PMID 23717811, 2013). "The PI3K/mTOR pathway is activated in over half of low-grade gliomas." (PMID 23717811, 2013). "Although previous studies have reported that interruption of the PI3K class I/AKT/mTOR pathway with siRNAs or pharmacological inhibitors can induce autophagy in human glioma cells, we observed that under our conditions insulin does not inhibit autophagy in the mock-treated U87MG cells." (PMID 24349488, 2013). "Indeed, preclinical studies of combined EGFR and mTOR inhibitors have shown antiproliferative and proapoptotic effects against gliomas." (PMID 22530122, 2012). "Recently, an Akt-independent PLCγ-PKCα-mTOR pathway was identified in glioma." (PMID 24212795, 2011). "To further evaluate whether senescence induced by nutlin-3a in glioma cells is depending on mTOR signaling, we evaluated activity of mTOR pathway after treatment." (PMID 21483692, 2011). "Iripallidal (i) induced apoptosis, (ii) inhibited Akt/mTOR and STAT3 signaling, (iii) altered molecules associated with cell cycle and DNA damage, (iv) inhibited telomerase activity and colony forming efficiency of glioma cells." (PMID 20576128, 2010). "As mTOR blockade is a biomarker of therapeutic efficacy in glioma, the unique ability of Iripallidal to inhibit both Akt and mTOR can be exploited as novel anti-glioma therapy." (PMID 20576128, 2010). "U87 human glioma cells are PTEN-negative with increased PI3K-AKT/mTOR pathway activity." (PMID 19347037, 2009).
glioma (continued). "By synthesizing current knowledge, this review seeks to establish a framework for leveraging mTOR-targeted therapies within the emerging field of cancer neuroscience, with the goal of improving oncological and neurological outcomes for patients with glioma and related conditions." (PMID 41301687, 2025). "Moreover, some Chinese scholars have found that dysfunction of the mTOR signaling pathway is closely related to tumor formation, and mTOR protein is highly expressed in glioma, suggesting that abnormal mTOR signaling may be an important pathogenesis of glioma." (PMID 39944825, 2025). "Additionally, studies have shown that 6’s anti-GBM effect may be due to inactivating the PKCδ/STAT3 signaling pathways, triggering cytotoxic autophagy in glioma cells by suppressing PI3K/AKT/mTOR and enhancing TMZ’s pro-apoptotic effect via NF-κB modulation." (PMID 40076568, 2025). "Therefore, investigating whether SERPINB6 targets the PI3K/AKT/mTOR axis could be of significant importance in glioma management." (PMID 40665565, 2025). "Additionally, inhibition of ADAM10 prevents the release of NLGN3 into the TME, thereby suppressing high-grade glioma xenograft growth by blocking NLGN3-mediated activation of the phosphoinositol 3-kinase (PI3K)/mechanistic target of rapamycin (mTOR) signaling pathway." (PMID 41163091, 2025). "Therefore, we hypothesize that CAMK2B may modulate glioma progression through the PI3K/AKT/mTOR signaling pathway." (PMID 41050075, 2025). "Furthermore, in glioma (U251) cells, triptolide triggers G2/M phase arrest while promoting apoptosis and autophagy, associated with the activation of ROS/c-JNK signaling pathways and inhibition of AKT/mTOR signaling [1009]." (PMID 40490812, 2025). "In addition, mTOR, PI3K/AKT, and AMPK signaling are closely associated with glycolysis in gliomas.Overall, glycolysis is intricately linked to the activity of glioma cells; therefore, it is a promising target for novel glioma treatment approaches." (PMID 39272133, 2024). "As for this insufficient pharmacologic effect, additional implication from the array data would be that glioma cell migration could also be affected through the link between mTOR signaling and focal adhesion kinases (FAK), represented by the higher-ranking GO term “cell adhesion”." (PMID 38481314, 2024). "Similarly, mTOR inhibitors have been shown to reduce IDHmut glioma growth rate and D2HG levels." (PMID 38026690, 2023). "Hence, unravelling the multi-faceted interactions between ROS metabolism and PI3K/AKT/mTOR, paving a way out for apoptosis will undoubtedly provide novel insights on the identification of exploitable vulnerabilities for treatment of hyperactive PI3K/AKT/mTOR tumors like glioma." (PMID 37025487, 2023). "However, in vitro studies confirmed a dysfunctional influence of glioma cells on GABAergic neurons due to a hyperactivated mTOR signaling pathway, leading to decreased electrophysiological activity, particularly of parvalbumin-containing “fast-spiking” GABAergic interneurons (FS)." (PMID 38275375, 2023). "Other interesting factors discovered in this finding were that PrP silencing in glioma cell lines causes increased autophagy due to induction of LC3-II, an increase in Beclin 1, and simultaneous decreases in p62, Bcl-2, and the phosphorylation of 4E-BP1, a target of mTOR autophagy signaling." (PMID 36674920, 2023). "Therefore, we speculate that the TME combinatorial treatment used in this study had potentially hampered glioma proliferation by ROS-induced inactivation of PI3K/ATK/mTOR pathway on induction of apoptosis." (PMID 37025487, 2023). "We then explore whether hirudin‐induced autophagy in glioma cells is associated with the activity of the mTOR signalling pathway by detecting the phosphorylation levels of ULK1, P70S6K, and 4EBP1, which are the core proteins of the mTOR signalling pathway." (PMID 37539490, 2023). "And ipatasertib could act on PI3K/mTOR signaling in glioma cells." (PMID 37158834, 2023).